STAT3 (signal transducer and activator of transcription 3)
Diseases named in the same sentence as STAT3 in open-access papers (continued):
Sharing a sentence is not in itself a finding about the gene and the disease.
gastric cancer (continued). "Additionally, STAT3 has been demonstrated to be prominently expressed in various cancer cells, including gastric cancer." (PMID 35844184, 2022). "Moreover, IL-23 was recently found to increase cell migration and invasion of gastric cancer cells by inducing epithelial-to-mesenchymal transition via the STAT3 pathway." (PMID 36313672, 2022). "In this study, HEIH can also promote glycolysis of gastric cancer cells by regulating STAT3." (PMID 36246567, 2022). "Dopamine and cAMP-regulated phosphoprotein Mr-32000 (DARPP-32) can induce the expression of Ang2 in gastric cancer cells by regulating signal transducer and activator of transcription 3 (STAT3), promoting angiogenesis and mediating the occurrence and development of gastric cancer." (PMID 35874764, 2022). "Given the strong link between elevated miR-21 expression and increased Stat3 activity, we hypothesized a functional involvement of miR-21 during the Stat3-dependent initiation, maintenance, and progression of gastric cancer." (PMID 35053428, 2022). "In this study, we identified a new regulatory axis lncRNA RPSAP52/miR-665/STAT3 in gastric cancer." (PMID 35322746, 2022). "STAT3 promotes gastric cancer cell proliferation, invasion, and chemoresistance." (PMID 35757757, 2022). "Besides, TGR5 activation can inhibit the proliferation and migration of gastric cancer cells by inhibiting STAT3 and NF-κB signaling pathways." (PMID 36338742, 2022). "The main transcription factors that drive gastric cancer-related inflammation are NF-kB and STAT3." (PMID 35892729, 2022). "Tumor-activated neutrophils infiltrate the lesion and play a key role in the progression of gastric cancer via STAT3-related mechanisms, and the interaction of gastric cancer cells with tumor neutrophils promotes their migration, epithelial-mesenchymal transformation (EMT), and invasion." (PMID 36033825, 2022). "Therefore, STAT3 is regarded as an attractive target for gastric cancer therapy (Mali, 2015; Yu, Pardoll, & Jove, 2009)." (PMID 36034876, 2022). "STAT3 depletion is confirmed to enhance cell apoptosis in gastric cancer." (PMID 35322746, 2022). "Upregulation of miR-499-5p via STAT3 signaling pathway could increase gastric cancer cell proliferation and invasion by targeting PDCD4." (PMID 35402235, 2022). "Following stimulating by CD4+ T cell, the immunophenotype of TA-MSCs undergoes significant changes, as they acquire the ability to overexpress PD-L1 in a STAT3-dependent manner and subsequently activate cancer cell-intrinsic PD-1/mTOR signaling to assist gastric cancer development." (PMID 36324128, 2022). "Our findings not only revealed a novel mechanism through which chemotherapy induced CSCs in gastric cancer via GM-CSF-miRNA-Jak2/Stat3 signaling, but also provided an experimental evidence for appropriate dose reduction of adjuvant chemotherapy in treatment of cancer patients." (PMID 35600882, 2022). "In addition, berberine and curcumin have been found to target survivin and STAT3 in gastric cancer cells." (PMID 36144625, 2022). "Phosphorylation of STAT3 promoted the progression of gastric cancer." (PMID 35646647, 2022). "In summary, TGR5 activation can inhibit the proliferation and migration of gastric cancer cells via the suppression of STAT3 and NF-κB signal pathways, and thus TGR5 could be used to diagnose and treat gastric cancer in the future." (PMID 36014536, 2022). "A study identified NR4A3 as the target gene of STAT3 in gastric cancer." (PMID 35747513, 2022). "Furthermore, knockdown of RNF6 significantly increased the cleavage of PARP and promoted cell apoptosis through the SHP-1/STAT3 signaling pathway, which eventually inhibits gastric cancer cell growth." (PMID 35223862, 2021).
gastric cancer (continued). "Since STAT3 phosphorylation is a crucial event in the signaling pathway, triggered by IL-6 in MMP-2 up-regulation in gastric cancer cells, we analyzed the STAT3 phosphorylation status following the rIL-6 exposure before and after preincubation with LPE in T88 and T93 cells." (PMID 34885656, 2021). "Furthermore, a highly activated STAT3 pathway is associated with chemoresistance and overall poorer prognosis in PDAC and gastric cancer patients." (PMID 34440697, 2021). "The upregulation of SIRT1 in gastric cancer could be the result of a feedback mechanism that reduces the damaging effects of STAT3 signaling." (PMID 34885041, 2021). "As the abnormal expression and dysregulation of STAT3/5 have been reported in various malignancies including gastric cancer, targeting of STAT3/5 phosphorylation may be beneficial for gastric cancer treatment." (PMID 33807326, 2021). "Thus, the STAT3-NF-κB-fascin signaling axis was identified as a therapeutic target to block the invasion and migration of gastric cancer cells." (PMID 34194957, 2021). "The authors suggested that SIRT1 upregulation may compensate for the damaging effect induced by constitutive activation of STAT3 in gastric cancer." (PMID 33886682, 2021). "Luteolin also disrupts Hsp90 and STAT3 expression in gastric cancer cells." (PMID 34539403, 2021). "Also, circ_0000117 promoted cell proliferation and invasion in gastric cancer via regulating STAT3 expression by competitively binding to miR-337-3p." (PMID 34057019, 2021). "Previous study has proven that the epithelial-mesenchymal transition (EMT) process of gastric cancer cells could be induced by IGF-1 through the IGF-1R/STAT3 signaling pathway so that cancer cells would achieve metastasis." (PMID 34804946, 2021). "Inhibition of STAT3 in gastric cancer overexpressing ZIPK might have potential to improve the efficacy of cisplatin." (PMID 34375503, 2021). "Although bisulfite pyrosequencing and epigenetic treatment confirmed that miR-193a was epigenetically silenced in gastric cancer cell lines, ChIP-PCR found that it may be indirectly affected by STAT3." (PMID 33718136, 2021). "Additionally, in this study, we compared the methylation profile of three pairs of gastric cancer patients, based on the STAT3 activation status." (PMID 33886682, 2021). "Contradictory to studies showing that AKT inhibitors can target multiple RTKs in various cancer cell types, the PI3K/mTOR inhibitor BEZ235 did not significantly alter the activity of different STAT3-regulating RTKs in PTEN-deficient gastric cancer cells." (PMID 33431808, 2021). "In gastric cancer, miR-30a-3p mediates cancer cell invasion via STAT3/MMP11 signaling." (PMID 34182542, 2021). "Our previous study demonstrates that CMTM3 suppresses metastasis of gastric cancer through the STAT3/EMT signaling pathway by interacting with Rab5 to facilitate EGFR degradation and CMTM3 may serve as a prognostic and predictive biomarker in gastric cancer." (PMID 34560882, 2021). "Genetic manipulation of STAT3 altered T1012G-mediated cytotoxicity of gastric cancer cells." (PMID 34544479, 2021). "Further in vivo experiments confirmed that, combination treatment of circUBE2Q2 knocking down and STAT3 inhibitor has synergistic effects on the gastric cancer growth inhibition, which provides a possibility to enhance the sensitivity of targeted drugs to gastric cancer through targeting circUBE2Q2." (PMID 34611143, 2021). "Constitutive activation of JAK/STAT signaling may confer epigenetic silencing of the STAT3 indirect target and tumor suppressor microRNA, miR-193a in gastric cancer." (PMID 33718136, 2021). "Overexpressed lncRNA HAGLROS induced by STAT3 promoted the metastasis of gastric cancer." (PMID 34513693, 2021). "Similar to SRC, FYN is an SFK that is overexpressed in GC and is positively correlated with metastasis and may promote gastric cancer metastasis by activating STAT3-mediated epithelial-mesenchymal transition." (PMID 33479376, 2021).
gastric cancer (continued). "In the present study, galangin reduced the phosphorylated JAK2 and STAT3 in MGC 803 cells at 12 h, and the inhibitory effect of galangin on cell viability of MGC 803 cells was counteracted by STAT3 overexpression, indicating galangin inhibited gastric cancer in a STAT3-dependent manner." (PMID 33981228, 2021). "We have previously demonstrated methylation of multiple STAT3 targets in gastric cancer patients." (PMID 33886682, 2021). "In summary, β-blocker pretreatment could improve the propagation and therapeutic efficacy of T1012G in human gastric cancer by regulating STAT3-PKR signaling cascade, even in the presence of type I IFNs." (PMID 34544479, 2021). "As activation of STAT3 was related to poor prognosis in gastric cancer, these results suggested that methylation of C11orf87 might independent to cancer progression." (PMID 33886682, 2021). "To prove this hypothesis, we analyzed the expression levels of PTEN and STAT3 kinase activity in tumor tissues from 75 gastric cancer patients." (PMID 33431808, 2021). "Herein, we postulated that hypermethylation of C11orf87 may serve as a “vestigial marker” for constitutive activation of STAT3 in gastric cancer." (PMID 33886682, 2021). "For example, SIRT6 inhibits the JAK2/STAT3 pathway to suppress the growth of gastric cancer." (PMID 33510943, 2021). "Ma and his colleagues demonstrated that IL-11 could enhance the chemoresistance of gastric cancer cells by modulating the JAK/STAT3 signaling pathway." (PMID 34149927, 2021). "SIRT‐1 was shown to inhibit the proliferation and metastasis of gastric cancer cells through activating the STAT3/MMP‐13 signaling pathway by inducing phosphorylation/acetylation of matrix metalloproteinase 13 (MMP‐13) and STAT3 in both in vivo and in vitro models." (PMID 33133558, 2020). "This highlights how directed targeting of RNF180 to gastric cancer cells could be used to block RhoC-driven activation of STAT3." (PMID 32915198, 2020). "Zhang and his colleagues showed that Tan IIA could suppress gastric cancer cells growth by down-regulating STAT3 and FOXM1 expression." (PMID 32265690, 2020). "Inhibiting the STAT3/MSK1/NFATc2 signaling axis significantly suppressed gastric cancer cell proliferation and xenograft tumor growth, which provides a potential novel approach for gastric carcinogenesis intervention by regulating aberrant epigenetic and transcriptional mechanisms." (PMID 32041943, 2020). "PLB also inhibited Stat3 pathway through the induction of SHP1 activity in stomach cancer cells." (PMID 33344645, 2020). "Moreover, eupatilin inhibits angiogenesis in gastric cancer cells by blocking STAT3-mediated vascular endothelial growth factor (VEGF) expression." (PMID 31913462, 2020). "PVT1 has been shown to interact with transcription factor STAT3 in gastric cancer cell lines." (PMID 32083000, 2020). "High expression of CMTM3 might correlate with favorable prognosis in gastric cancer, which not only inhibits the EGF-mediated tumorigenicity by promoting Rab5 activity, but also suppresses metastasis of gastric cancer via the STAT3/Twist1/EMT pathway." (PMID 33282744, 2020). "ATO is known to inactivate STAT3 in gastric cancer cells through SHP-1 induction." (PMID 33256086, 2020). "IL-11 levels are significantly higher in a murine model of gastric cancer, and IL-11 is the major factor that drives STAT3 activation and corresponding inflammation in murine gastric and colon cancer models, as well as human cell line xenograph models of these cancers." (PMID 32765502, 2020). "To explore the possible interplay between STAT3 signaling and epigenetic alterations in gastric cancer development, in the current study, we investigated the epigenetic changes of aberrant histone modifications and the involvement of STAT3 pathways in gastric carcinogenesis." (PMID 32041943, 2020). "This evidence revealed that STAT3 constitutively activated in gastric cancer." (PMID 32265690, 2020).
gastric cancer (continued). "It has been shown that inhibition of the Jak-STAT3 signaling pathway could inhibit cell proliferation in gastric cancer cells." (PMID 33114089, 2020). "In addition, TAMs promote the epigenetic silencing of gelsolin through DNA methyltransferase 1 activity induced by CCL5/CCR5/STAT3 signaling in gastric cancer cells." (PMID 31892854, 2020). "There is also evidence that Fascin is a putative target of β-catenin–T-cell factor (TCF) signaling in colon and gastric carcinomas, Transforming growth factor beta (TGFβ) signaling in breast carcinomas and STAT3/ Nuclear factor kappa B (NF-kB) signaling in breast and gastric carcinomas." (PMID 33212856, 2020). "Similarly, NC inhibited cell growth and angiogenesis through suppression of the STAT3 pathway in gastric cancer." (PMID 30847386, 2019). "Furthermore, to explore the role of STAT3 in the inhibition of MUC4 by ALA in gastric cancer cells, AGS, BGC-823, and MKN-28 cells were incubated with 0, 0.5, 1, or 2 mM ALA for 24 h in RPMI with 10% FBS when cell confluence was 60%." (PMID 31915505, 2019). "Treatment with cisplatin alone causes side effects that increase the CSC-like properties of gastric cancer cells by activating the interleukin-6 (IL-6)-mediated signal transducer and activator of transcription 3 (Stat3) signaling; however, cotreatment with SFN improves the chemotherapy efficacy." (PMID 31126043, 2019). "To explore the mechanism, we found that the effect of ALA on gastric cancer cells might be related to STAT3." (PMID 31915505, 2019). "Additionally, the protein level of phospho Janus kinase 2 (JAK2) was decreased by Genipin treatment, indicating that the Stat3/JAK2/Mcl-1 pathway is suppressed by Genipin treatment in gastric cancer cells." (PMID 31351462, 2019). "Not surprisingly, enhanced expression of IL‐11 could increase STAT3 activation to favor gastric cancer development." (PMID 31273847, 2019). "HOXA11 had the ability to change the stemness property of gastric cancer cells via forming a novel positive feedback loop with Stat3, and through such reprogramming, to modulate the adhesion, migration/invasion and anti-apoptosis phenotype of gastric cancer cells." (PMID 31695791, 2019). "However, the cytotoxic effect of quercetin against EBV-infected gastric cancer cells has been reported to occur also independently of STAT3 inhibition." (PMID 31547402, 2019). "MIA-602 downregulates p21-activated kinase and STAT3 and NFκB in gastric cancer cells." (PMID 31392398, 2019). "It has been reported that STAT3 plays a role in human gastric cancer development." (PMID 31915505, 2019). "Thus, our study suggests that Genipin is useful as a new therapeutic agent for gastric cancer targeting JAK/Stat3 and Mcl-1." (PMID 31351462, 2019). "Given the important role of IL‐11 in gastric cancer, our study may provide an alternative route toward IL‐11 regulation and possible disruption of IL‐11/STAT3 pathway." (PMID 31273847, 2019). "Furthermore, inhibition of JAK2/STAT3 pathway suppresses the growth of gastric cancer in vitro and in vivo." (PMID 31540495, 2019). "Decreased degradation of IL‐11 mRNA may subsequently augment STAT3 signaling to facilitate gastric cancer development." (PMID 31273847, 2019). "Therefore, SFN inhibits the CSC-like viability of gastric cancer cells by regulating the expression levels of miR-124 and its target genes, IL-6R and Stat3." (PMID 31126043, 2019). "Our previous studies found that aberrant activation of JAK/STAT signaling could lead to epigenetic silencing of STAT3 targets in gastric cancer." (PMID 31194837, 2019). "Constitutive activation of STAT3 is closely related to poor prognosis of gastric cancer." (PMID 30202514, 2018). "A recent study showed that ATO may inhibit the signal transducer and activator of transcription 3 (STAT3) activation in alpha-fetoprotein-producing gastric cancer cells, and thereby induce apoptosis." (PMID 29409467, 2018).
gastric cancer (continued). "Specifically, upregulation of STAT3 predicts poor outcome of gastric cancer." (PMID 29720137, 2018). "In summary, SHP-1 as an effective phosphatase for inactivation of JAK2/STAT3 might be applied in gastric cancer and pantoprazole showed significant modulating effect on SHP-1/JAK2/STAT3 signaling axis in stomach cancer." (PMID 30202514, 2018). "Thus, inhibition of STAT3 activation is considered a key point of attack to prevent the formation and invasion of gastric cancer." (PMID 29409467, 2018). "Taken together, our data suggest that SHP-1 might have a mediating role in the inhibitory effect of pantoprazole on STAT3 activity and migration or invasion of gastric cancer cells." (PMID 30202514, 2018). "Inhibiting STAT3 activity is an important issue for treating gastric cancer." (PMID 30202514, 2018). "Most importantly, either suppressing DNMT enzyme activity, or treatment with demethylation agent, or interfering with CCL5/CCR5/STAT3 pathway led to decreased in vivo tumor growth, suggesting several possible routes of epigenetic inhibition of gastric cancer development." (PMID 30200265, 2018). "Our results suggest that the anti-tumorigenic effect of pantoprazole might be mediated by the modulation of SHP-1/p-STAT3 axis in gastric cancer." (PMID 30202514, 2018). "Our data suggest that SHP-1 may play a pivotal role in downregulating STAT3 induced by pantoprazole in gastric cancer cells." (PMID 30202514, 2018). "The results of an experiment with mice revealed that the oncogenesis of melanoma and prostatic or gastric cancers could be inhibited by blocking of the IL-6/STAT3 signal pathway." (PMID 29693005, 2018). "Restoration of chemoresistance by ATO in gastric cancer cells might be related to inactivation of STAT3 via induction of SHP-1." (PMID 29409467, 2018). "The both cooperatively work to inhibit phosphorylation of STAT3 in gastric cancer cells." (PMID 30202514, 2018). "STAT3 is also tightly involved in the development of skin and gastric cancers in mouse models." (PMID 29693005, 2018). "This in turn downregulated expression of Snail1, a target gene of STAT3 and a marker of mesenchymal transition in gastric cancer cells, and upregulated expression of E-cadherin, a target gene of Snail1 which directly represses E-cadherin expression in epithelial cells." (PMID 29409467, 2018). "Indeed, STAT3 is a key transcription factor for carcinogenesis, invasion and modulation of microenvironments in gastric cancer." (PMID 29409467, 2018). "However, most of the STAT3 inhibitors for gastric cancer have been confined to experimental studies." (PMID 29409467, 2018). "Interestingly, it was recently reported that STAT3 can bind to the promoter region of the EZH2 gene in gastric cancer cells, implicating STAT3 as direct regulator of EZH2." (PMID 29728695, 2018). "Besides other pro-cancer properties, activated STAT3 was shown to stimulate the expression of TLR2 in gastric carcinoma cells." (PMID 29467931, 2018). "To verify this hypothesis, we first examined the expression of STAT3 and activated STAT3 (p-Y705) in 5 gastric cancer cell lines." (PMID 29152078, 2017). "Moreover, the overexpression of the Notch1 receptor intracellular domain (N1IC) elevates gastric cancer progression, including tumor growth, metastasis, migration and invasion, by promoting the intercellular interplay of STAT3 and the Twist promoter." (PMID 28881855, 2017). "Moreover, silencing IL-6 expression in CAFs or inhibiting JAK2/STAT3 pathway in gastric cancer cells impairs tumor peritoneal metastasis induced by CAFs in vivo." (PMID 28186964, 2017). "Moreover, knockdown the expression of IL-6 in CAFs by RNAi or inhibiting JAK2/STAT3 pathway in gastric cancer cells by the specific inhibitor AG490 significantly retards the tumor peritoneal metastasis induced by CAFs in vivo." (PMID 28186964, 2017).